MUC13 (mucin 13, cell surface associated)
Diseases named in the same sentence as MUC13 in open-access papers (continued):
Sharing a sentence is not in itself a finding about the gene and the disease.
tumor (continued). "Moreover, miR-145 injections in xenograft mice suppressed tumor growth through inhibition of MUC13 and HER2 as its downstream target." (PMID 34307654, 2021). "MUC13 mucin is aberrantly over-expressed in PanCa and the exogenous expression of MUC13 increases tumorigenic features, such as enhanced cell proliferation, cell motility, cell invasion, and in vivo tumor growth." (PMID 31906106, 2019). "MUC13 is aberrantly overexpressed in PanCa and the ectopic expression of MUC13 augments tumorigenic features, such as enhanced cell proliferation, cell motility, cell invasion, and in vivo tumor growth." (PMID 31906106, 2019). "MUC13 expression was detected by immunohistochemical staining in tumor specimens." (PMID 27911274, 2017). "Thus, this suggests that miR-145 inhibits MUC13 and its related targets and leads to tumor regression in xenograft mice." (PMID 25277192, 2014). "Additionally, intratumoral injections of miR-145 in xenograft mice inhibited tumor growth via suppression of MUC13 and its downstream target, HER2." (PMID 25277192, 2014). "The MUC13 mucin is aberrantly overexpressed in PanCa and the exogenous expression of MUC13 augments tumorigenic features such as enhanced cell proliferation, cell motility, cell invasion, and in vivo tumor growth." (PMID 25277192, 2014). "Moreover, IHC analyses of tumor tissues revealed an inhibition of MUC13 expression in miR-145 treated tumors." (PMID 25277192, 2014). "This revealed a strong correlation between MUC13 and miR-145 in both tumor and normal tissues." (PMID 25277192, 2014). "Our study provides important insights into the role of miR-145 in a well-known tumor-promoting network that involves MUC13, which may provide a route to therapeutic miRNA intervention in PanCa." (PMID 25277192, 2014). "The RT‐qPCR analysis revealed that all target genes (MUC3A, MUC4, MUC13, and MUC16) are significantly overexpressed in tumor samples as compared to control samples." (PMID 41142718, 2025). "The expression profiling of overexpressed MAMs explored the cancer‐specific overexpression of MUC3A, MUC4, MUC13, and MUC16 in tumor samples as compared to control." (PMID 41142718, 2025). "MUC13, on the other hand, displays elevated levels in LUAD tissues and cells, indicating its potential significance in this tumor type." (PMID 40655139, 2025). "Throughout the observation duration, the growth curve indicated a marked increase in tumor volume for the RUNX1-overexpressing cells relative to the control, an elevation considerably diminished upon MUC13 suppression." (PMID 39309442, 2024). "CIDEC was significantly down-regulated in tumor tissues, while EPS8L3, MUC13 and PLEKHS1 were significantly highly expressed in tumor tissues." (PMID 37978443, 2023). "MUC13 and YAP1 expression was significantly higher in the tumor area compared with the adjacent normal areas." (PMID 37793774, 2023). "Higher expression of MUC13 and YAP1 was observed at different tumor stages compared with adjacent normal samples, highlighting the clinical significance of this novel molecular interaction." (PMID 37793774, 2023). "The expression levels of the known IGC markers MUC13 and CDH1718 and the known DGC markers COL1A2 and SPARC19 increased from GMCs to tumor cells in the tree." (PMID 35087207, 2022). "In contrast, three membrane‐bound MUCINs (MUC1, MUC13, and MUC15), one atypical MUCIN (EMCN), and one secretion MUCIN (MUC6) were significantly downregulated in the tumor samples (p < 0.05)." (PMID 34327857, 2021). "Previous studies have found that the expression levels of MUCINs, including MUC1, MUC4, MUC12, MUC13, MCAM, and LAMA4 were correlated with poor survival of ccRCC patients, and/or promotion of tumor cell proliferation in vitro." (PMID 34327857, 2021). "Similar to their in vitro findings, siRNA knockdown of MUC13 reduced total NF-κB p65 protein and reduced BCL-XL expression in tumor cells." (PMID 33808549, 2021).
tumor (continued). "IHC was conducted to examine the expression of selected target markers MUC4, MUC13, and MUC20 in 186 ESCC resection samples and the relationships between their expression and tumor regression grade was analyzed." (PMID 26673820, 2016). "In addition, although GSDME−/− tumour cells lost the resistance to digestive enzymes, re-expression of exogenous MUC1 or MUC13 largely restored their resistance, and the co-expression of MUC1 and MUC13 achieved the greatest resistance." (PMID 35292781, 2022). "In the present study, we observed that Muc13 was upregulated in the absence of Muc4, suggesting its tumor-promoting role in CRC." (PMID 35255004, 2022). "In addition, MUC13 is suspected to play a role in the expression of other oncogenic proteins, such as PAK1 and S100A4 which play role in tumor migration, invasion and metastasis." (PMID 34522225, 2021). "Mucins may act as oncogenes and tumour-promoting (e.g., MUC1, MUC13), and/or tumour-suppressing factors (e.g., MUC15)." (PMID 30875782, 2019). "Expression of eight additional genes associated with EMT was initially analyzed individually; a good correlation between tumor sensitivity to BI 853520, and gene expression was observed for MUC13 and POF1B but not for TWIST1." (PMID 29472531, 2018). "Regarding the intestinal mucins, a significant increase in MUC13 mRNA expression was seen in the paired tumor tissues compared to the adjacent non-tumor and FD tissues whereas no significant alterations in expression were seen for MUC2 and MUC4 mRNA among the different sample types." (PMID 37085819, 2023). "The expression of MUC13 in PDAC tumor microenvironment has not been reported yet." (PMID 34522225, 2021). "The results demonstrated that MUC4 and MUC20 were expressed at low levels in the tumor tissue samples obtained from chemosensitive patients (TRG1/2/3), whereas the expression of MUC13 did not significantly correlate with TRG." (PMID 26673820, 2016). "In addition, in YBX1 knockout tumour cells, replenishment of NLS-YBX1 but not NES-YBX1 upregulated MUC1 and MUC13." (PMID 35292781, 2022). "In the present study, we first analyzed the tumor and adjacent non-tumor tissues of the GC patient cohorts and the biopsy tissues of the FD patients to measure the relative mRNA expression of gastric (MUC1, MUC5AC, MUC6) and intestinal (MUC2, MUC4, MUC13) mucins." (PMID 37085819, 2023).
cancer (35 papers, 2008 to 2026). A tumor composed of atypical neoplastic, often pleomorphic cells that invade other tissues. "The overexpression of MUC13 can cause abnormal cellular polarity, which increases the adaptability of cancer." (PMID 39682235, 2024). "It has been demonstrated that mucins such as MUC4 and MUC13 are associated with cancer development; the circulating level of MUC16 is even used to monitor patients with ovarian cancer." (PMID 29062084, 2017). "Additionally, investigations of membrane-bound mucin genes (MUC1, MUC3, MUC4, and MUC13), associated with altered O-linked glycosylation in various cancers, were investigated through the GEO database (GSE16581) and underwent qPCR." (PMID 38274327, 2024). "MUC13 (Mucin 13 cell surface associated; down-regulated in P2 and S1 in CT) is associated with epithelial barrier function and its overexpression indicates cancer." (PMID 28002487, 2016). "Therefore, MUC13 serum and urine immunoassay might be developed as a screening method or diagnostic marker for cancer." (PMID 27911274, 2017). "For instance, the formation of the MUC4-ERBB2-ERBB3-NRG1 complex can suppress apoptosis, while MUC13 has been identified as an oncogenic glycoprotein that promotes cancer cell growth." (PMID 39744399, 2024). "Specifically, MUC13 is aberrantly expressed in different types of cancers and its functional mechanisms have been explored in multiple studies." (PMID 39309442, 2024). "Mechanistically, RUNX1 exerts direct regulation over MUC13, activating the Wnt/β-catenin pathway, a critical mediator in cancer progression and EMT." (PMID 39309442, 2024). "MUC13 has been shown to be oncogenic and plays a role in activating key survival pathways in cancer." (PMID 37793774, 2023). "MUC13 is often elevated not only in various malignant tumors but also in certain benign pathologies, so it seems to be non-specific disease biomarker." (PMID 37395858, 2023). "Elucidation of cellular and molecular mechanisms by which MUC13 activates YAP1-mediated oncogenic signaling pathways can provide important insights toward cancer metastasis." (PMID 37793774, 2023). "MUC13, a transmembrane glycoprotein, has exhibited oncogenic functions in various cancers, including CRC." (PMID 37793774, 2023). "This strengthens the argument that MUC13 is critical in driving cancer aggressiveness and metastasis through the YAP1-dependent oncogenic pathway." (PMID 37793774, 2023). "Another study reported that MUC13 knockdown significantly weakened the potential for cell migration and invasion, indicating that MUC13 acts as a governing role in maintaining the aggressiveness of cancer." (PMID 37395858, 2023). "MUC13 expression has been correlated with cancer progression, disease outcome, patient’s poor prognosis, and biophysical changes in cancer cells." (PMID 37793774, 2023). "Muc4 maintains the intestinal homeostasis by upregulation of Muc2 and Fam3D (guardians of the gut) and downregulation of cancer-promoting mucin (Muc13)." (PMID 35255004, 2022). "MUC13 is a cell surface mucin glycoprotein and plays a critical role in cancer cell proliferation and apoptosis." (PMID 32719746, 2020). "Since our results showed a marked upregulation of glucose uptake and lactate production, we evaluated effects of MUC13 expression on the important proteins involved in enhanced cancer cell metabolism." (PMID 29467405, 2018). "Consistent with our results, a growing body of literatures found that overexpression and aberrant localization of MUC13 was observed in other cancers." (PMID 27911274, 2017). "We selected 6 genes (MUC4, MUC13, MUC20, BMP7, AKT3, and SMAD3) that were closely associated with the development and progression of cancer to validate the conclusions drawn from the gene expression profiling analysis." (PMID 26673820, 2016). "MUC13 is expressed abundantly by colorectal, ovarian and gastric human cancers, and is considered an early marker for cancer screening." (PMID 23776483, 2013).
cancer (continued). "MUC1 and MUC13, for instance, are highly expressed in such carcinomas when compared to normal colon cells." (PMID 21152207, 2009). "Nevertheless, MUC13 is significantly elevated in some cancer patients." (PMID 37395858, 2023). "Thus, investigating if MUC13, besides providing anoikis resistance to cancer cells, can facilitate the next steps of metastasis is vital." (PMID 37793774, 2023). "For the first time, we discovered in this study the critical role of MUC13 in cancer metastasis." (PMID 37793774, 2023). "In addition, MUC13 can be used as a marker for early cancer screening, providing a promising target for targeted therapy." (PMID 37978443, 2023). "MUC13 increases cell growth, migration, invasion, and colony formation of cancer cells." (PMID 37793774, 2023). "As not all pre-malignant gastric conditions will eventually evolve into cancer, such oral taxa-MUC13 signatures in patients with pre-cancerous stadia could also help predict the potential to further evolve into cancer." (PMID 37085819, 2023). "MUC13 is typically expressed in the intestine and is correlated with the gastric colon and cancer." (PMID 36700475, 2022). "This phenomenon implies that the combination of HER-2 and EDF-like domain may be implicated in the modulations of cellular characteristic and MUC13 may play a significant role in the development of cancer." (PMID 27911274, 2017). "These indicate that MUC13 may become a novel prognostic biomarker and predict for chemosensitivity of cancer." (PMID 27911274, 2017). "These implied that MUC13 might become an effective therapeutic target for cancer." (PMID 27911274, 2017). "To further investigate if YAP1 is downstream to MUC13, in YAP1-mediated survival of cancer cells in an anchorage-independent environment, we knockdown YAP1 expression in ectopic MUC13 expressing (SW480+MUC13) cells." (PMID 37793774, 2023). "Another mucin, mucin 13 (MUC13), promotes the progression of various cancer types, including CC, through induction of ERBB2 expression and NF-κB activation." (PMID 32708604, 2020). "Many other cancer-related genes showed up differentially expressed in PDAC, including MUC2, MUC5B, MUC13, ALDH3A1, CDCA7, and CCL2." (PMID 31379917, 2019). "Studies have shown that cell surface mucin 13 ( MUC13) protects the degradation of β-catenin by interacting with GSK-3β, thereby increasing the nuclear translocation of β-catenin and promoting the occurrence, development, invasion and immunosuppression of cancer by signaling transduction." (PMID 37395858, 2023).
infection (18 papers, 2011 to 2026). The state of being infected such as from the introduction of a foreign agent such as serum, vaccine, antigenic substance or organism. "Conversely, the loss of MUC13 secretion following infection was intriguing because it is a transmembrane mucosal protein with pro-inflammatory properties." (PMID 32075873, 2020). "A year later, a study published by Zhang and collaborators revealed the association of the MUC13 haplotypes with resistance to F4ab/ac ETEC, suggesting the involvement of variants of this gene in infection resistance." (PMID 41595487, 2026). "Upregulation of Muc13 expression remained until 52 weeks post-infection, confirming earlier suggestions about its potential involvement in promoting the transition from chronic inflammation to cancer." (PMID 35692057, 2022). "In BALB/c mice experimentally infected with H. heilmannii s.s., expression of the secreted mucin Muc6 and the transmembrane mucin Muc13 was upregulated in the first 9 weeks post-infection." (PMID 35692057, 2022). "Under normal conditions, MUC13, like most transmembrane mucins, functions to protect cells from infection and damage by forming a barrier along the mucosal surface of those cells." (PMID 30700707, 2019). "More recently, the mRNA expression level of MUC13 is shown to be down-regulated in the inflamed intestine cells of porcine induced by F4ac ETEC strain infection." (PMID 23922972, 2013). "We, therefore validated, using quantitative reverse transcription polymerase chain reaction (PCR), upregulation of the clearest example of an infection status marker gene, MUC13, in P.berghei-infected primary human hepatocytes, as well as in P.berghei-infected Huh7.5.1, HepG2, and HC04 cells." (PMID 30700707, 2019). "MUC13 plays an important modulatory role in epithelial response to damage and infection." (PMID 29282153, 2017). "Within 4 h of infection with a commensal or pathogenic E. coli O157:H7 strain, upregulation of the transcription of proteins that participate in gastrointestinal defenses was seen, including the mucins (MUC2 and MUC13), the structural component of gastric mucus; trefoil factor." (PMID 32636253, 2020). "Following infection with SARS-CoV-2, multiple mucin genes showed significantly positive correlations in the digestive tissues, particularly MUC1, MUC12 and MUC13." (PMID 38563680, 2024). "In contrast, G5P infection decreased expression of transmembrane mucin genes significantly (MUC12, MUC16 and MUC21) or numerically (MUC1, MUC4, MUC13 and MUC20)." (PMID 37848925, 2023). "Comparing the time-dependent changes between 3 hours and different times after infection, several genes like FZD4, LPR4, and MUC13 which were upregulated compared to the uninfected controls were also upregulated over time." (PMID 37615437, 2023). "We have previously found that the expression of porcine MUC13 and MUC4 was down-regulated in IPEC-J2 cells post infection with the same F4ac ETEC strain, and the expression of ITGB5 was not significantly decreased." (PMID 23922972, 2013). "Secondly, we assessed the relative effects of ITGB5 and MUC13 on mRNA expression of the two mucin genes (MUC4 and MUC20) in response to 3 h infection with ETEC strain 200 (MOI = 8∶1) at 44 h after siRNAs transfection." (PMID 23922972, 2013). "Mucins such as Muc2 and Muc13 also were detected in all selected tissues in our study, further suggesting that SVCV invasion may lead to secondary infection." (PMID 33897703, 2021). "Gene expression analysis revealed a significantly increased expression of Muc13 in the stomach corpus in the long-term but not in the short-term infection group." (PMID 34768765, 2021). "In addition, at intermediate points of infection (12 and 24 hpi), the MUC13 IFA intensity correlates with the dramatic transcriptional induction of MUC13 during late-stage hepatic infection." (PMID 30700707, 2019).
infection (continued). "This induction of MUC13 also seems to be specific to exoerythrocytic infection, as IFA analysis for MUC13 in asexual blood stage parasites (with MUC13 Antibody #2—LifeSpan Biosciences #LS—C345092) shows no colocalization with parasites, only a faint MUC13 signal along the RBC membrane." (PMID 30700707, 2019). "It is possible that in other systems MUC13 is exported to the site of infection but is not observed in micrographs because this space is extracellular and protein can be washed away." (PMID 30700707, 2019). "Second, we observe no MUC13 mRNA during early hepatocyte infection (2 hpi) or asexual blood stage infection, but do detect strong parasite HSP70 signal later during exoerythrocytic development." (PMID 30700707, 2019).
inflammation (3 papers, 2012 to 2021). Aberrant reaction of the microcirculation characterized by movement of fluid and leukocytes from the blood into extravascular tissues. "The individual mucins were investigated for different reasons: MUC2—the main secreted mucin—and MUC13—the main transmembrane mucins—are essential for the integrity of the intestinal mucus barrier; a distortion of their expression increases the susceptibility to develop intestinal inflammations." (PMID 34685068, 2021). "In the present study, we demonstrated that the transcript levels for muc1, muc2, muc3, muc4, muc5b and muc13 in lung tissue were unaltered, whereas muc5ac transcript expression was significantly increased during allergen-induced airway inflammation in mice." (PMID 28205598, 2017).
adenocarcinoma (2 papers, 2023). A common cancer characterized by the presence of malignant glandular cells. "In comparison, only 28% of the adenocarcinoma samples demonstrated nuclear expression of MUC13 and YAP1." (PMID 37793774, 2023). "More specifically, Lactobacillus was found to be significantly more abundant in adenocarcinomas with high MUC4 and MUC13 expression." (PMID 37085819, 2023).
immune dysfunction (1 paper, 2023). "Unlike MUC1, IL-22 also regulates MUC13 expression via p38 MAPK activation, a signaling pathway involved in TLR4-mediated cell proliferation and immune dysfunction in IBD." (PMID 37174625, 2023).